AR (androgen receptor)
Diseases named in the same sentence as AR in open-access papers (continued):
Sharing a sentence is not in itself a finding about the gene and the disease.
prostate carcinoma (continued). "The combination of ONC201, darolutamide, and enzalutamide worked synergistically to reduce cellular viability, induce apoptosis, and downregulate AR signaling in a castration-resistant prostate cancer model." (PMID 41020897, 2025). "The androgen receptor (AR) signaling pathway is the primary driver of prostate cancer initiation and progression, including the development of castration-resistant prostate cancer (CRPC)." (PMID 41020902, 2025). "ITRI-148 achieves sustained AR signaling suppression and prevents AR-V7–driven reactivation, representing a promising candidate for advanced prostate cancer therapy." (PMID 41237749, 2025). "While substantial research on AR in prostate cancer continues to evolve, studies have expanded beyond prostate cancer to explore AR's role in other tumors, such as melanoma, gastric cancer, hepatocellular carcinoma (HCC), and breast cancer." (PMID 40583627, 2025). "Most studies looked at the role of AR in prostate cancer, where the AR drives epigenetic heterogeneity at enhancers through AR binding sites, affecting response to therapy." (PMID 40406098, 2025). "The development of targeted therapies for prostate cancer reflects the central role of the androgen receptor (AR) signaling pathway, along with the recognition of molecular vulnerabilities such as DNA repair deficiencies and prostate-specific antigens." (PMID 41228293, 2025). "Research has shown that androgens can significantly increase the expression of CYP4F2 and CYP4F3 through androgen receptor (AR) in prostate cancer cells, while PON1 activity is modulated by estrogen through HDL metabolism pathways." (PMID 40115349, 2025). "Although androgen deprivation therapy (ADT) combined with androgen receptor inhibitors has shown significant efficacy in treating prostate cancer, resistance to treatment remains a major challenge, particularly in patients with metastatic prostate cancer." (PMID 40178629, 2025). "Although bicalutamide has historically played a role in the management of prostate cancer, its clinical relevance has declined with the advent of more effective androgen receptor inhibitors." (PMID 40244528, 2025). "Androgen deprivation therapy (ADT) is a standard treatment for advanced prostate cancer, aiming to reduce androgen levels and inhibit AR activity." (PMID 39858458, 2025). "Among them, AR inhibitors, such as bicalutamide, flutamide, oestrogens, or ketoconazole, have been the main choice for prostate cancer treatment in recent years." (PMID 40458791, 2025). "The majority of prostate cancers progressing despite AR inhibition retain expression of the AR and AR-activated pathways." (PMID 40454483, 2025). "In summary, oxidative stress, driven by increased ROS production following androgen deprivation, plays a central role in prostate cancer progression by activating AR signaling pathways and inducing treatment resistance." (PMID 41281744, 2025). "Abnormal activation of the AR signaling pathway is the fundamental reason for the occurrence and development of prostate cancer." (PMID 40224223, 2025). "To gain further insight into their possible mode of action, we focused on one of the key molecular targets in prostate cancer–the androgen receptor (AR)." (PMID 40747210, 2025). "In an ongoing phase 2 trial in prostate cancer, the effect of combining an Src inhibitor with an AR inhibitor versus an AR inhibitor alone on the development of EMT in prostate cancer was compared, but no definitive results have been published." (PMID 39917165, 2025). "UA selectively inhibits AR-positive prostate cancer cells by suppressing AR signaling, and its efficacy has been confirmed in enzalutamide-resistant cells." (PMID 40568370, 2025).
prostate carcinoma (continued). "Prostate cancer also demonstrates subtype dependence, with androgen receptor (AR)-positive versus AR-independent contexts engaging different acetylation–autophagy axes (e.g., PCAF/δ-catenin versus TPD52–CMA)." (PMID 41213956, 2025). "For advanced prostate cancer, the androgen receptor (AR) pathway plays a critical role in tumor cell survival, establishing endocrine therapies targeting this pathway as the cornerstone of treatment." (PMID 41079787, 2025). "Luteolin, a natural flavonoid, exhibits potent antiproliferative effects on prostate cancer cells, particularly AR-positive LNCaP cell line." (PMID 41020902, 2025). "Punicalagin effectively inhibits the androgen receptor (AR), a protein essential for the development and metastasis of prostate cancer." (PMID 40018013, 2025). "During the last decade, AR-Vs have gained clinical interest as potential biomarker in prostate cancer." (PMID 40859365, 2025). "The AR signaling axis and transcriptional activities drive the proliferation of the hormone-sensitive form of prostate cancer." (PMID 39858071, 2025). "Here, Dicer is a pivotal regulator of prostate cancer progression, influencing key processes such as cell proliferation, apoptosis, miRNA biogenesis, and androgen receptor signaling." (PMID 40034825, 2025). "TET2 inhibition and decreased 5hmC levels activate key prostate cancer‐related pathways, including the mechanistic target of rapamycin kinase (mTOR) and AR pathways, which drive prostate cancer development." (PMID 40599235, 2025). "As a control, we performed similar enrichment with the reference prostate cancer AR peaks (GSE70079)." (PMID 39731353, 2025). "These preliminary findings support the rationale for developing bioportides targeting the protein phosphatase 1–androgen receptor axis as a novel therapeutic strategy in prostate cancer." (PMID 41092058, 2025). "In the setting of bone metastasis, G6PD expression in prostate cancer cell is upregulated by cytokine secreted by cells within the bone and through androgen receptor (AR) signaling." (PMID 41514554, 2025). "It is well-established that AR overexpression and signaling pathways mediated by ARs are critical for the survival of prostate cancer cells." (PMID 40001982, 2025). "It is known that the growth and development of prostate cancer usually depends on androgen stimulation such as testosterone, and androgen receptor inhibitors are one of the commonly used drugs for the treatment of prostate cancer." (PMID 39781351, 2025). "In an in vitro model of prostate cancer, it was shown that estrogen and selective ER agonists affected prostate cancer growth but only in AR-positive cell lines." (PMID 40023399, 2025). "Prostate cancer (PC) remains a significant health challenge, with androgen receptor (AR) signaling playing a pivotal role in its progression." (PMID 40214455, 2025). "Triptolide inhibits the binding of RNA polymerase II, TFIIH, and AR to the target enhancer, resulting in an increased responsiveness of metastatic castration-resistant prostate cancer cells (mCRPCs) and xenograft models to enzalutamide treatment." (PMID 40143065, 2025). "Treatment of prostate cancer cells with miR-125b mimics or modulators affected androgen receptor signalling pathways." (PMID 40869103, 2025). "The landscape of prostate cancer biology centers around the androgen receptor (AR) signaling pathway, which plays a pivotal role in disease development, progression, and therapeutic responses." (PMID 40432836, 2025). "We also investigated the androgen receptor (AR) modulation of GGT family gene expression in prostate cancer cells." (PMID 40094020, 2025). "In prostate cancer, androgen receptor (AR) directly interacts with FOXA1, driving cancer growth and survival." (PMID 39731353, 2025).
prostate carcinoma (continued). "While β-catenin has been shown to interact with the androgen receptor (AR), the key driver of prostate cancer, extensive studies indicate that GSK3β positively regulates AR activation and promotes tumor progression independently of Wnt signaling." (PMID 40072085, 2025). "Novel strategies for prostate cancer therapy are required to overcome resistance to next-generation AR inhibitor." (PMID 41200193, 2025). "Acetylation of the AR can affect its activation, nuclear translocation, and transcriptional activity, potentially impacting resistance to prostate cancer treatments." (PMID 41079787, 2025). "CMV influences AR signaling, a known pro‐proliferation pathway in prostate cancer by promoting gene expression of the AR." (PMID 40493023, 2025). "Specifically, RARγ has been shown to be deregulated in prostate cancer and to influence the androgen receptor cistrome in malignant cell lines." (PMID 39633177, 2025). "Its downregulation in prostate cancer inhibits cancer development by suppressing the transcription activation of cyclin D2 or AR." (PMID 40356745, 2025). "ADT, commonly used in prostate cancer treatment, has been recognized for its ability to block AR signaling in T cells, thereby restoring T cell activation by inhibiting the PD-1/PD-L1 pathway." (PMID 40303343, 2025). "The androgen receptor (AR) remains a crucial therapeutic target in prostate cancer, especially in castration-resistant prostate cancer (CRPC)." (PMID 40573283, 2025). "Homozygous deletion of RB locus and loss of RB function facilitate the development of a castrate-resistant prostate cancer via E2F-mediated upregulation of the AR." (PMID 40304827, 2025). "Studies have demonstrated that direct AR antagonists have displayed noteworthy efficacy in the treatment of prostate cancer." (PMID 40017595, 2025). "In this study, we formulated D-Lin-MC3-DMA-LNPs encapsulating siRNA against the androgen receptor (AR), a key driver in prostate cancer." (PMID 40115963, 2025). "In prostate cancer, AR signaling is a major driver of tumorigenesis by regulating genes involved in proliferation, survival, and differentiation." (PMID 40940929, 2025). "Androgen deprivation therapy (ADT) or hormone therapy remains the gold standard treatment for AR-positive prostate cancer." (PMID 40479062, 2025). "Such a multifaceted approach, combining mRNA expression analysis of PCA3, PSMA, and AR genes with sPD-L1 levels, provides a comprehensive understanding of prostate cancer’s characteristics." (PMID 39859417, 2025). "Prostate cancer heterogeneity, tumor clonality, and AR plasticity, under selective pressure by ADT, remain significant challenges." (PMID 40867349, 2025). "This study sheds light on the involvement of HIC1 in prostate cancer and proposes that the regulation of the AR/IRS2 axis represents a potential mechanism through which HIC1 impacts the development of prostate cancer." (PMID 41050263, 2025). "Efforts to exploit the dependence of SPOP-mutant prostate cancer cells on dysregulated AR signaling are ongoing, with small molecule inhibitors and gene-editing techniques being explored as potential therapeutic strategies." (PMID 40432836, 2025). "The expression and transcriptional activity of PPARG can be inhibited by AR in human prostate cancer cells." (PMID 40458476, 2025). "Emerging evidence reveals that androgen receptor (AR) facilitates immune evasion in prostate cancer through transcriptional suppression of MHC class I molecules." (PMID 41019050, 2025). "Single-cell transcriptomic profiling of human prostate cancers, both pre- and post-androgen deprivation therapy, revealed an association between liver kinase B1 (LKB1) pathway inactivation and AR independence." (PMID 39743630, 2025). "The combination of Rac1 inhibitors and AR antagonists suppresses AR gene expression in androgen-sensitive prostate cancer cells." (PMID 40948788, 2025).
prostate carcinoma (continued). "Because HSPs play a key role in cellular responses to stress, we next interrogated the impact of different cellular stresses (AR targeting, heat shock, and radiation) on AR-FL and AR-V7 protein expression in VCaP prostate cancer cells." (PMID 39787247, 2025). "AR signaling inhibitors have improved overall survival for men with advanced prostate cancer, but treatment resistance is inevitable." (PMID 39787247, 2025). "These genetically engineered mouse model studies further corroborate that LKB1 inactivation is able to suppress the AR pathway in prostate cancer." (PMID 39743630, 2025). "We further examined the effect of FTI treatment using lonafarnib in a clinically relevant setting with a patient-derived xenograft (PDX) model from a prostate cancer metastatic lesion harboring the SPOP F133L mutation and AR expression." (PMID 40662365, 2025). "While the AR signaling pathway remains a central therapeutic target in prostate cancer, long-term reliance on ADT often leads to CRPC, which is associated with poor clinical outcomes." (PMID 40959108, 2025). "In primary androgen therapy–responsive prostate cancer, AR signaling increases the expression of DNA repair genes and, in parallel, promotes localized prostate cancer radio-resistance by accelerating repair after ionizing radiation." (PMID 40978127, 2025). "They function as coregulators of AR16–20, and their inhibition impairs AR-positive prostate cancer growth." (PMID 41044247, 2025). "Here we report that in androgen receptor-positive LNCaP prostate cancer cells, the hormone-dependent 5′-tRNALysCUU half promoted cell proliferation by facilitating cell cycle progression." (PMID 40471969, 2025). "The androgen receptor (AR) is a pivotal regulator of growth and survival of prostate cancer (PCa) and the majority of lethal castration-resistant prostate cancers (CRPC) remain reliant on AR signaling." (PMID 40446667, 2025). "AR plays a central role in prostate cancer, with the activity of its signaling pathway directly influencing the proliferation and survival of tumor cells." (PMID 40008000, 2025). "Activation of the AR drives the expression of several hundred genes comprising the prostate carcinoma transcriptome, which is recapitulated in LNCaP_FGC cells." (PMID 40956611, 2025). "The transient orexin receptor pathway activity at 0 h corresponds to OX1R’s dual role in prostate cancer - baseline receptor presence in LNCaP cells with therapeutic potential through androgen receptor translocation inhibition." (PMID 40607016, 2025). "AR has been well studied in prostate cancer, and inhibition of AR activity and androgen deprivation therapy are critical therapeutic tools in the treatment of metastatic prostate cancer." (PMID 40118451, 2025). "For prostate cancer, antiandrogen drugs such as bicalutamide work similarly to tamoxifen-ER, and it competitively bind to AR to prevent testosterone activation in prostate cancer." (PMID 40023399, 2025). "The BD2-selective inhibitor ABBV-744 (AbbVie) showed robust preclinical efficacy in AR-positive prostate cancer and AML models, displacing BRD4 from AR-containing super-enhancers, inhibiting AR-dependent transcription, and reducing tumor growth in xenografts." (PMID 41335282, 2025). "The degradation of AR specifically inhibits the proliferation of hormone-dependent prostate cancer cells." (PMID 40771930, 2025). "Disrupting androgen receptor-regulated metabolic pathways further sensitizes prostate cancer cells to radiation-induced DNA damage." (PMID 39859224, 2025). "Although vitamin E possesses antioxidant properties, its impact on the expression and function of the androgen receptor is considered the primary mechanism through which it inhibits prostate cancer progression." (PMID 40362574, 2025).
prostate carcinoma (continued). "This process promotes primary cilia formation and enhances GLI3R production in the Hedgehog signaling pathway, ultimately inhibiting androgen receptor activity and suppressing the progression of prostate cancer." (PMID 39785769, 2025). "Loss‐of‐function experiments demonstrate that CMV promotes cell survival, proliferation, and androgen receptor signaling, identifying it as a therapeutic target in castration‐sensitive and castration‐resistant prostate cancer." (PMID 40493023, 2025). "Quercetin modulates ROS production, interferes with MAPK, Akt, and NF-κB signaling pathways, and targets prostate cancer cells with different AR statuses." (PMID 41278192, 2025). "Understanding the nuances of AR signaling is critical, particularly regarding how the modulation of Cyclin D1 and Bcl-2 contributes to prostate cancer development and progression." (PMID 40008000, 2025). "A-485 demonstrates lineage-specific antiproliferative activity in 124 cancer cell lines, particularly showing significant effects in hematologic malignancies and AR+ prostate cancer." (PMID 40032852, 2025). "In conclusion, androgen receptor and protein phosphatase 1 interaction remains a promising target in prostate cancer therapy." (PMID 41092058, 2025). "We conducted a de novo characterization of the circRNA landscape in prostate carcinoma cell line LNCaP along neuroendocrine transdifferentiation, using two AR-dependent and two AR-independent biological replicates." (PMID 40008007, 2025). "According to most guidelines, androgen receptor pathway inhibitors are currently important for the treatment of almost all advanced prostate cancers." (PMID 41092154, 2025). "Punicalagin effectively inhibits androgen receptor (AR), a protein essential for the development and metastasis of prostate cancer." (PMID 40018013, 2025). "ARV‐771 affects kinase‐dependent oncogenic signaling indirectly by inducing the strong degradation of BRD4, a master regulator of transcriptional programs in AR+ prostate cancer." (PMID 41362117, 2025). "ARV-110: This PROTAC is specifically designed to degrade the androgen receptor (AR), which is crucial in driving prostate cancer." (PMID 39851497, 2025). "A study indicated that PC‐SPES reduced the expression of AR, which increased cell cycle arrest, cell death, and limited antioxidant prostate cancer cell proliferation." (PMID 41164269, 2025). "AR itself shows a similar pattern of stage- and context-dependent tumor suppression in prostate cancer." (PMID 39858088, 2025). "In prostate cancer, LTFe enhances ferroptosis by promoting lactotransferrin-mediated iron transport, a process disrupted by androgen receptor (AR) signaling." (PMID 40919170, 2025). "Dysregulation of AR signaling, often seen in advanced prostate cancer, contributes to treatment resistance and disease progression." (PMID 40432836, 2025). "In prostate cancer, CREB3L4 plays a critical role in promoting cell proliferation and is functionally linked to AR-regulated oncogenic pathways." (PMID 41155247, 2025). "Non-coding RNAs, particularly long non-coding RNAs (lncRNAs), have emerged as potential therapeutic targets due to their role in regulating the AR signaling pathway and their significant contribution to prostate cancer progression and drug resistance." (PMID 40008000, 2025). "This suggests that hard ECM contributes to disease aggressiveness of prostate cancer despite driving down the androgen receptor signaling." (PMID 40115748, 2025). "Collectively, these results underscored the intricate relationship between metabolic dysregulation and epigenetic remodeling in driving lineage plasticity and supporting the tumorigenic expansion of AR-independent prostate cancer." (PMID 39743630, 2025). "It has been reported that ACSM1 and ACSM3 are directly regulated by AR in prostate cancer, and they promote FAO to fuel cancer cells." (PMID 41281744, 2025).